GPAT4 (glycerol-3-phosphate acyltransferase 4)
Description:
Converts glycerol-3-phosphate to 1-acyl-sn-glycerol-3-phosphate (lysophosphatidic acid or LPA) by incorporating an acyl moiety at the sn-1 position of the glycerol backbone. Active against both saturated and unsaturated long-chain fatty acyl-CoAs. Protects cells against lipotoxicity.
Synonyms: 1-AGPAT 6; LPAAT-zeta; TSARG7; AGPAT6; DKFZp586M1819; LPAATZ
Tractability: Antibody: UniProt predicts a signal peptide or a membrane-spanning region. PROTAC: ubiquitination databases record sites on it; its protein half-life has been measured.
Target class: Enzyme; Transferase
Gene: Protein-coding gene on chromosome 8 (41,577,187 to 41,625,001, forward strand). Ensembl gene ENSG00000158669.
Subcellular location: Endoplasmic reticulum membrane
Pathways (Reactome):
Metabolism: Synthesis of PA
Gene Ontology:
Molecular function: 1-acylglycerol-3-phosphate O-acyltransferase activity; glycerol-3-phosphate O-acyltransferase activity; protein binding; acyltransferase activity; lysophosphatidic acid acyltransferase activity
Biological process: acyl-CoA metabolic process; phosphatidylcholine biosynthetic process; triglyceride biosynthetic process; lactation; lipid biosynthetic process; phosphatidic acid biosynthetic process; CDP-diacylglycerol biosynthetic process
Cellular component: endoplasmic reticulum; endoplasmic reticulum membrane; membrane
Genetic constraint (gnomAD): Loss-of-function variants: 17 observed, 58.9 expected, observed/expected ratio (o/e) 0.29, 90% interval 0.2 to 0.43. The upper end of that interval is the gene's LOEUF score, 0.43, which puts it in group 1 of 6, group 1 being the genes least tolerant of losing a copy. Missense variants: 377 observed, 593.43 expected, observed/expected ratio (o/e) 0.64, 90% interval 0.58 to 0.69. Synonymous variants: 204 observed, 216.32 expected, observed/expected ratio (o/e) 0.94, 90% interval 0.84 to 1.06.
Homologues: Orthologues: chimpanzee GPAT4 (99% identical), macaque GPAT4 (99% identical), guinea pig GPAT4 (98% identical), mouse Gpat4 (98% identical), rabbit GPAT4 (97% identical), rat Gpat4 (92% identical), pig GPAT4 (92% identical), dog GPAT4 (90% identical), tropical clawed frog gpat4 (85% identical), zebrafish gpat4 (80% identical), Drosophila melanogaster Gpat4 (47% identical), Caenorhabditis elegans acl-4 (46% identical), and 2 more. Paralogues in human: GPAT3 (66% identical), LPCAT2 (19% identical), LPCAT4 (17% identical), LPCAT1 (17% identical).
Diseases named in the same sentence as GPAT4 in open-access papers:
GPAT4 is named in the same sentence as 19 diseases in open-access papers, as found by Europe PMC text mining. Sharing a sentence is not in itself a finding about the gene and the disease. The quoted sentences say what the papers report.
Obesity (7 papers, 2013 to 2025). Accumulation of substantial excess body fat. "The aim of this study is to investigate if central GPAT4 is associated with obesity-related depression and its underlying mechanism." (PMID 34054732, 2021). "GPAT4−/−-deficient mice exhibit a 25% reduction in body weight and a resistance to diet-induced and genetically-induced obesity with increased energy expenditure." (PMID 30813330, 2019). "Another microsomal isoform, GPAT4, is also associated with obesity." (PMID 30813330, 2019). "Therefore, this study aims to investigate whether central GPAT4 is associated with obesity-related depression and its underlying mechanism." (PMID 34054732, 2021). "The aim of the present study was to investigate whether common and low-frequency variation in AGPAT6, encoding a novel GPAT enzyme, GPAT4, was associated with type 2 diabetes, obesity, dyslipidemia or indices of insulin resistance and insulin secretion in a large Danish population." (PMID 24156295, 2013). "Mutations in GPAT4, which encodes the enzyme glycerol-3-phosphate acyltransferase, are associated with various activities and may be a potential therapeutic target for the prevention and treatment of diseases related to energy metabolism, obesity, insulin resistance, and type 2 diabetes." (PMID 37906284, 2024). "Glycerol-3-phosphate acyltransferases 4 (GPAT4) is involved in triacylglycerol synthesis and plays an important role in the occurrence of obesity." (PMID 34054732, 2021). "Gene overexpression and gene knockout experiments confirmed that GPAT4 plays an important role in the development of obesity, liver steatosis and insulin resistance." (PMID 34054732, 2021). "GPAT4 is the key rate-limiting enzyme in the synthesis of triacylglycerols in the glycerophosphate pathway and plays an important role in the development of obesity." (PMID 34054732, 2021). "Our findings suggest that hippocampal GPAT4 may participate in HFD induced depression through AMPK/CREB/BDNF pathway, which provides insights into a clinical target for obesity-associated depression intervention." (PMID 34054732, 2021). "In conclusion, we demonstrate that hippocampal GPAT4 might participate in HFD induced depression by activating AMPK, CREB and BDNF pathways, which provides insights into a clinical target for obesity-associated depression intervention." (PMID 34054732, 2021). "Absence of GPAT4 leads to subdermal lipodystrophy, a significant reduction in triacylglycerol content in adipose tissue and liver, and resistance to diet-induced obesity." (PMID 40004102, 2025).
Insulin resistance (5 papers, 2013 to 2024). Increased resistance towards insulin, that is, diminished effectiveness of insulin in reducing blood glucose levels. "Like mitochondrial GPAT1, GPAT4 is also associated with hepatic lipid accumulation and contributes to the development of insulin resistance." (PMID 29799006, 2018). "Another isoform, GPAT4, has also been associated with insulin resistance." (PMID 38893234, 2024). "Studies involving GPAT4 gene knockout mice fed a high-fat diet have revealed that GPAT4 is responsible for insulin resistance in the liver and muscle." (PMID 38893234, 2024). "Compared with wild-type mice, GPAT4-/- (gene knockout) mice lose weight, have subcutaneous lipodystrophy, reduce triacylglycerol (TAG) content in adipose tissue and liver, and improve insulin resistance." (PMID 34054732, 2021). "In addition, GPAT4−/− mice were protected from DIO and the development of insulin resistance in the liver and muscle cells through decreased content of di16:0 PA." (PMID 29799006, 2018).
lipodystrophy (4 papers, 2013 to 2025). A congenital or acquired disorder characterized by abnormal loss or redistribution of the adipose tissue in the body. "GPAT4 deficiency in mice causes subdermal lipodystrophy, suggesting that GPAT4 plays a role in TAG accumulation in subdermal adipocytes." (PMID 30813330, 2019).
depression (1 paper, 2021). "In our future studies, we will use specific hippocampal GPAT4 knockout mice to further confirm the role of GPAT4 in the hippocampus in the development of depression." (PMID 34054732, 2021). "The present study reveals that high fat diet induced GPAT4 overexpression in hippocampus, suggesting that GPAT4 in the hippocampus might play a role in diet-induced depression." (PMID 34054732, 2021). "However, whether central GPAT4 is involved in the development of depression remains unclear." (PMID 34054732, 2021).
Epithelial Ovarian Cancer (1 paper, 2025). "We present evidence that GPAT4, a gene linked to both lipid metabolism and ferroptosis, may also play a role in ovarian cancer’s resistance to platinum-based treatments." (PMID 40722736, 2025). "High expression levels of GPAT4 may be linked to ferroptosis and platinum resistance in ovarian cancer." (PMID 40722736, 2025). "This study suggested that further screening of patients with drug-resistant ovarian cancer and those with platinum-sensitive ovarian cancer after sequencing may reveal an association between GPAT4 expression and platinum resistance in ovarian cancer." (PMID 40722736, 2025). "Specifically, GPAT4 had a median IHC mark of 2 in platinum-sensitive ovarian cancer and a median IHC mark of 6 in platinum-resistant ovarian cancer." (PMID 40722736, 2025). "Next, we focused on the target of the key enzyme of lipid metabolism, GPAT4, in promoting tumor growth through ferroptosis in platinum-resistant ovarian cancer cells." (PMID 40722736, 2025). "GPAT4 was selected for further analysis based on its significant differential hydroxymethylation in platinum-resistant ovarian cancer and its reported involvement in ferroptosis and lipid metabolism." (PMID 40722736, 2025). "According to the immunohistochemical staining results, GPAT4 expression in platinum-resistant ovarian cancer (n = 34) was significantly increased compared to that in platinum-sensitive tissues (n = 56, p < 0.001)." (PMID 40722736, 2025). "High expression of both SLC7A11 and GPAT4 was independently correlated with poor OS, highlighting the significance of this integrated metric as a prognostic factor in ovarian cancer." (PMID 40722736, 2025). "To evaluate the impact of the combined IHC score grouping of SLC7A11 and GPAT4 on the prognosis of ovarian cancer patients, we categorized the tissues that tested positive for both SLC7A11 and GPAT4 as the copositive group (n = 21)." (PMID 40722736, 2025). "The high expression of GPAT4 or SLC7A11 has been demonstrated to correlate with a poor prognosis in ovarian cancer patients from the TCGA-OC cohorts." (PMID 40722736, 2025). "Low expression of GPAT4 contributes to immediate sensitivity to platinum-based chemotherapy in ovarian cancer." (PMID 40722736, 2025). "The potential diagnostic and therapeutic roles of GPAT4 and SLC7A11 in ovarian cancer are explored further in subsequent sections." (PMID 40722736, 2025). "In this study, GPAT4 was significantly superior to SLC7A11 as a stand-alone predictor of platinum-resistant ovarian cancer drug resistance (SLC7A11 IHC score AUC 0.908, SLC7A11 expression grouping AUC 0.874)." (PMID 40722736, 2025). "As an individual indicator, GPAT4 exhibited a strong predictive capability for drug resistance in ovarian cancer (GPAT4 IHC score AUC 0.917, GPAT4 expression group AUC 0.874)." (PMID 40722736, 2025). "However, GPAT4 inhibitors have rarely been applied in the field of platinum resistance prediction in ovarian cancer." (PMID 40722736, 2025). "Background/Objectives: This study aimed to determine whether the expression levels of GPAT4 and SLC7A11 are associated with survival outcomes and platinum resistance in epithelial ovarian cancer (EOC) patients." (PMID 40722736, 2025). "The study revealed that GPAT4/SLC7A11 is related to drug resistance and a poor prognosis in ovarian cancer." (PMID 40722736, 2025). "Furthermore, in comparison to the individual parameters (GPAT4 or SLC7A11 expression), a high co-expression level of GPAT4-SLC7A11 was identified as a more effective predictor of poor prognosis in ovarian cancer." (PMID 40722736, 2025). "Continuously, our follow-up study will provide insights into the mechanisms by which GPAT4 regulates platinum resistance in ovarian cancer, adding prospective evaluation, increasing the number of patients with EOC, and establishing a link between SLC7A11 and the regulation of GPAT4." (PMID 40722736, 2025).
Epithelial Ovarian Cancer (continued). "Moreover, the combination of GPAT4 and SLC7A11 was found to be a novel marker predicting platinum resistance in ovarian cancer." (PMID 40722736, 2025). "Our follow-up studies will continue to provide insights into the mechanisms by which GPAT4 regulates platinum resistance in ovarian cancer; we will increase the number of assessed patients with EOC and work to establish a link between SLC7A11 and the regulation of GPAT4." (PMID 40722736, 2025). "While the combined assessment of GPAT4 and SLC7A11 showed improved predictive ability compared with SLC7A11 alone, it was not as effective as using GPAT4 alone for predicting drug resistance in ovarian cancer." (PMID 40722736, 2025). "Finally, external validation in larger, independent patient cohorts and prospective clinical studies will be essential to confirm the prognostic and predictive value of GPAT4/SLC7A11 co-expression, particularly in the context of platinum resistance in epithelial ovarian cancer (EOC)." (PMID 40722736, 2025).
glaucoma (1 paper, 2020). Increased pressure in the eyeball due to obstruction of the outflow of aqueous humor. "The enzymes depicted in red are upregulated in glaucoma, for example LPIN2 and PLPP3, whereas the GPAT4 depicted in blue are downregulated." (PMID 32602905, 2020). "We investigated all enzymes in these families (at genomic/mRNA level) and found GPAT4 and LIPIN2 to be the only enzymes with statistically significant differences between control and glaucoma." (PMID 32602905, 2020).
glioblastoma (1 paper, 2023). The most malignant astrocytic tumor (WHO grade IV). "Furthermore, there is higher expression of AGPAT6/GPAT4 in glioblastoma tumor tissue than in healthy brain tissue." (PMID 37046844, 2023). "In particular, AGPAT5, AGPAT6/GPAT4, AGPAT8/ALCAT1/LCLAT1, AGPAT9/LPCAT1, and AGPAT11/LPCAT2 show higher expression in glioblastoma tumors than in healthy tissue." (PMID 37046844, 2023).
tumor (5 papers, 2021 to 2025). "In TCGA-LIHC paired samples, the transcript levels of GPAT2 and GPAT4 were found to be significantly higher in tumor tissue samples than in the respective adjacent normal tissue samples." (PMID 36845084, 2023). "Meanwhile, by analyzing the expression changes of 8 MMRGs between high-risk and high-risk groups, we know that SLC27A1, GPAT4, and TNFAIP8L3 were highly expressed in the prognosis of high-risk patients, which may be tumor promoting factors for OvCa." (PMID 37256178, 2023). "We observed that 4/7 FAS genes, GPAT4, CHP1, PCGF1, and GPI, show significant, negative hazard ratios (HR), consistent with a tumor suppressor signature, and that no other gene from our set shows a negative HR." (PMID 34764293, 2021).
cancer (2 papers, 2022 to 2024). A tumor composed of atypical neoplastic, often pleomorphic cells that invade other tissues. "Our findings have shown that expression of GPAT4 and DGAT1 were reduced in NAT10‐depleted cancer cells and palmitate‐loaded NAT10‐depleted cancer cells suggesting that NAT10 depletion implicates in reduced lipid droplet formation." (PMID 36149760, 2022).
infection (2 papers, 2019 to 2023). The state of being infected such as from the introduction of a foreign agent such as serum, vaccine, antigenic substance or organism. "Previously published data on N. benthamiana root infection by P. palmivora reported that NbGPAT6a, but none of the other members of the GPAT4/6/8 clade, showed a consistent and significant transcriptional induction during all stages of infection." (PMID 30980530, 2019).
GPAT4 also shares sentences with these, for which no sentence is quoted: Hepatic steatosis (3 papers); type 2 diabetes (3); breast carcinoma (1); diabetes (1); dyslipidemia (1); hypertriglyceridemia (1); non-alcoholic fatty liver disease (1); ovarian cancer (1); steatosis (1).